ASTILCS (antisense transcript of PTP4A3, liver carcinoma survival associated)
Gene: Long non-coding RNA gene on chromosome 8 (141,389,886 to 141,392,574, reverse strand). Ensembl gene ENSG00000244998.
Diseases named in the same sentence as ASTILCS in open-access papers:
ASTILCS is named in the same sentence as 1 disease in open-access papers, as found by Europe PMC text mining. Sharing a sentence is not in itself a finding about the gene and the disease. The quoted sentences say what the papers report.
Liver Carcinoma (1 paper, 2021). An epithelial or non-epithelial malignant neoplasm that arises from the liver. "We named this lncRNA ASTILCS (AntiSense Transcript Important for Liver Carcinoma Survival)." (PMID 33589614, 2021).